RBP4 (retinol binding protein 4)
Diseases named in the same sentence as RBP4 in open-access papers (continued):
Sharing a sentence is not in itself a finding about the gene and the disease.
liver dysfunction (5 papers, 2019 to 2025). "Interestingly, in these patients, liver cirrhosis was associated with further reduced RBP4 concentrations and RBP4 was correlated with markers of liver dysfunction." (PMID 31569348, 2019). "In contract, RBP4 gene deletion can enhance insulin sensitivity and a negative correlation between the expression level of serum RBP4 and the severity of liver dysfunction has been observed." (PMID 36267567, 2022). "Fourth, liver dysfunction, represented by elevated AST levels, may impair the synthesis of both RBP4 and albumin, further exacerbating the decline in nutritional and inflammatory balance." (PMID 40881125, 2025).
night blindness (5 papers, 2020 to 2024). Inability to see clearly in dim light. "Unlike fenretinide, another RBP4 antagonist, A1120 is neither a retinoid nor an agonist to RARα, the property of which may avoid the retinoids‐associated side effects, such as nyctalopia and delayed dark adaptation." (PMID 39031684, 2024).
osteoarthritis (5 papers, 2020 to 2026). A noninflammatory degenerative joint disease occurring chiefly in older persons, characterized by degeneration of the articular cartilage, hypertrophy of bone at the margins and changes in the synovial membrane. "RBP4 has been found secreted from synovial joints in patients with osteoarthritis and increased in patients with RA, associated with disease severity and has even been proposed as a marker of disease activity in RA patients." (PMID 40085146, 2025). "Targeting RBP4 may, therefore, represent a promising therapeutic strategy for delaying or preventing osteoarthritis progression, particularly in metabolically compromised conditions." (PMID 41744664, 2026). "Furthermore, RBP4 has recently been described to be present within the joints of osteoarthritis (OA) patients, and its levels have been correlated with the production of matrix-degrading enzymes in OA chondrocytes." (PMID 38275649, 2024).
osteoporosis (5 papers, 2021 to 2025). A condition of reduced bone mass, with decreased cortical thickness and a decrease in the number and size of the trabeculae of cancellous bone (but normal chemical composition), resulting in increased fracture incidence. "Some studies reported a positive association between RBP4 and BMD in postmenopausal women with osteopenia or osteoporosis." (PMID 38410670, 2024). "Fortunately in the past few years, novel adipokines have been identified such as visfatin, LCN2, nesfatin-1, RBP-4, apelin, and vaspin that may have osteoprotective/osteoanabolic effects and thus could serve as potential therapeutic targets for osteoporosis and other metabolic bone diseases." (PMID 36831180, 2023). "While one study showed that levels of RBP-4 may positively correlate with bone resorption marker CTX in males with T2D, another found a positive relationship between RBP-4 and BMD at different sites in postmenopausal women with osteopenia/osteoporosis." (PMID 36831180, 2023).
type 1 diabetes (5 papers, 2010 to 2022). "Patients with type 1 diabetes (T1D) display low serum RBP4 levels, and serum retinol is directly proportional to RBP4 in these patients and is also lowered." (PMID 35740038, 2022).
colon adenoma (4 papers, 2016 to 2023). An adenoma that arises from the colon. "We noticed that recently a report associated colon adenoma risk with high circulating levels of RBP4." (PMID 29190912, 2017). "In addition, several studies have suggested that high serum levels of rbp4 are associated with the development of colon adenomas." (PMID 37313408, 2023).
coronary artery calcification (4 papers, 2012 to 2021). Calcification of the coronary artery, used as a measure of coronary atherosclerosis, a risk factor for myocardial infarction. "In previous studies, increased RBP4 levels were associated with coronary artery calcification, and increased ROH and RBP4 are linked to an increased intima-media thickness." (PMID 25119682, 2015). "In postmenopausal women, increased RBP4 levels have been associated with coronary artery calcification." (PMID 25119682, 2015). "Retinol-binding protein 4 (RBP4), an adipokine primarily secreted by adipocytes and hepatocytes, has been implicated in oxidative stress, inflammation, and coronary artery calcification." (PMID 34168606, 2021). "Cross-sectional analyses related RBP4 levels to cardiometabolic risk factors, carotid artery intima-media thickness (CIMT), and coronary artery calcification (CAC)." (PMID 22587616, 2012).
endometriosis (4 papers, 2021 to 2023). The growth of functional endometrial tissue in anatomic sites outside the uterine body. "Retinol-binding protein 4 (RBP4) is an adipocyte-derived cytokine that contributes to the pathogenesis of endometriosis by increasing the viability, proliferation, and invasion of endometrial stromal cells." (PMID 35203301, 2022). "The levels of RBP4 in the fluids from the ovarian endometriomas were significantly higher than those in the PF of the women in the endometriosis group (P <0.05) and the control group (P < 0.05)." (PMID 34072419, 2021). "The levels of RBP4 in the PF were significantly higher in the endometriosis group compared with the control group (P < 0.05)." (PMID 34072419, 2021). "Further studies are necessary to clarify the mechanisms in which both the increased RBP4 levels and the aberrant retinoid signaling pathways are involved in the pathogenesis or pathophysiology of endometriosis." (PMID 34072419, 2021). "RBP4 levels were significantly higher in the PF of the women in the endometriosis group than in the controls." (PMID 34072419, 2021). "The immunoreactivity of RBP4 in the stromal cell was significantly higher in the eutopic endometrium of the patients with endometriosis compared with that of the controls only during the secretory phase (p = 0.012) (right)." (PMID 34072419, 2021). "RBP4 immunoreactivity was significantly higher in the ovarian endometriomas of women with advanced stage endometriosis than those of controls." (PMID 34072419, 2021). "The results confirmed that the levels of RBP4 were evidently higher in the PF and endometriotic fluid collected from the ovarian endometriomas of patients with endometriosis." (PMID 34072419, 2021). "A recent study showed that RBP4 is involved in the pathological process of endometriosis and could promote the activity, proliferation, and invasion of ectopic cells." (PMID 37662927, 2023). "Further studies are necessary to clarify the role of RBP4 in the pathogenesis of endometriosis." (PMID 38075048, 2023). "We validated that RBP4 was overexpressed in endometriosis patients." (PMID 37662927, 2023). "The results of this study strongly suggest that RBP4 might partake in the pathogenesis and/or pathophysiology of endometriosis by increasing the viability, proliferation, and invasiveness of endometrial cells." (PMID 34072419, 2021). "Here, we evaluated the possible role of RBP4 in the pathogenesis of endometriosis." (PMID 34072419, 2021). "Therefore, we aimed to evaluate the possible role of RBP4 in the pathogenesis of endometriosis in this study." (PMID 34072419, 2021). "The increased expression of RBP4 may lead to the progression of endometriosis via the activation of pro-inflammatory processes, cellular proliferation, and invasiveness." (PMID 34072419, 2021). "In order to validate the human XL proteome profile array data, we investigated whether the levels of RBP4 are elevated in the PF or endometriotic fluid collected from the ovarian endometriomas of patients with endometriosis, in comparison with the levels in the control samples." (PMID 34072419, 2021). "We could not explain the main origin of the increased of RBP4 levels in the patients with endometriosis, which is well known to be inversely associated with BMI or fat mass." (PMID 34072419, 2021). "The levels of angiogenin, CD105, ICAM-1, CXCL10, leptin, lipocalin-2, MMP-9, osteopontin, RBP4, PAI-1, ABP, CD31, TIM-2, and VCAM-1 were higher in the endometriosis group than in the control group." (PMID 34072419, 2021). "So far, only one study showed higher RBP4 levels in peritoneal fluid in the women with than without endometriosis." (PMID 38075048, 2023). "We compared the levels of RBP4 in the peritoneal fluid (PF) and tissues of women with and without endometriosis." (PMID 34072419, 2021).
endometriosis (continued). "We compared the levels of RBP4 in the tissues and peritoneal fluid (PF) of women with and without endometriosis and evaluated the in vitro effects of RBP4 on the viability, invasiveness, and proliferation of endometrial stromal cells (ESCs)." (PMID 34072419, 2021). "Among those soluble proteins significantly increased in PF in patients with endometriosis compared with controls, we found that the increase in the levels of RBP4 in endometriosis has not been reported to date." (PMID 34072419, 2021). "Among those soluble proteins shown to be higher in the endometriosis patients, the increase in the levels of RBP4 in endometriosis has not been reported to date." (PMID 34072419, 2021). "In addition, there are no reports about RBP4 and other uterine pathologies, which indicates that this signature is unique to endometriosis." (PMID 37662927, 2023). "Moreover, RBP4 immunoreactivity was significantly higher in ovarian endometriomas of women with advanced-stage endometriosis compared to women without endometriosis." (PMID 38075048, 2023). "In order to verify the increase in the levels of RBP4 determined by the human XL proteome profile array, we analyzed the levels of RBP4 in the PF of women with (n = 6) and without (n = 6) endometriosis, and in the fluids from ovarian endometriomas (n = 6) using ELISA." (PMID 34072419, 2021). "Considering that RBP4 serves as a signaling molecule activating downstream pro-oncogenic signaling pathways after binding to the membrane receptor STRA6, the data of the present study seem to support the idea that ectopic endometrial cells can exhibit malignant biological behaviors in endometriosis." (PMID 34072419, 2021). "However, there is no report about the relationship between PRF1 and RBP4 and other uterine pathologies, which suggests that these two might be unique signatures of endometriosis." (PMID 37662927, 2023). "However, the role of RBP4 in endometriosis has not been investigated to date." (PMID 34072419, 2021). "No direct link has been established between RBP4, G2MB, or PRF1 and endometriosis, necessitating further investigation." (PMID 37662927, 2023).
fibrosis (4 papers, 2008 to 2024). the formation of excess fibrous connective tissue in an organ or tissue in a reparative or reactive process. "Importantly, high RBP4 levels could be a marker of NAFLD development, and the lower levels of RBP4 may also be an indicator of the progression ot NASH with fibrosis among NAFLD disease stages." (PMID 33925827, 2021).
gastric cancer (4 papers, 2021 to 2025). A primary or metastatic malignant neoplasm involving the stomach. "Genes associated with lymph node metastasis in human gastric cancer (e.g., Rbp4, Igf2, Fn1) are not significantly upregulated in rats, indicating a lower potential for lymph node metastasis in MNNG-induced rat gastric cancer." (PMID 41211438, 2025).
glomerulopathies (4 papers, 2022 to 2025). "Because tubular injury may contribute to the loss of renal function in GDs, urinary tubular markers (including RBP4) seem to constitute a promising source of biomarkers for glomerular diseases." (PMID 36011513, 2022). "This complex RBP4 fatty acid form was only identified in urine in the presence of a glomerulopathy." (PMID 35216460, 2022).
Hypercholesterolemia (4 papers, 2015 to 2025). An increased concentration of cholesterol in the blood. "In accordance with the present data, a positive association between RBP-4 and hypercholesterolemia is found in several studies." (PMID 33133591, 2020). "Higher concentrations of RBP-4 were also observed in patients with positive parental history of CAD as well as hypercholesterolemia." (PMID 33133591, 2020). "Among these proteins, the RBP4 has been taken into accounts as a major linkage between hypercholesterolemia, adipose tissues, liver and kidney." (PMID 27103892, 2015). "These evidences lend support to the decrease of RBP4 and TTR in human serum associated with hypercholesterolemia." (PMID 27103892, 2015). "A decrease of RBP4 as a consequence of hypercholesterolemia might be attributable to the inflammation of adipose tissues." (PMID 27103892, 2015). "Six proteins including retinol-binding protein 4 (RBP4), transthyretin (TTR), gelsolin, haptoglobin, complement factor B (CFB) and CD5 antigen-like protein (CD5L) were identified to play imperative roles in lipid metabolism and inflammatory processes as a consequence of hypercholesterolemia." (PMID 27103892, 2015).
liver cancer (4 papers, 2021 to 2025). An epithelial or non-epithelial malignant neoplasm that arises from the liver. "Given the strong association of RBP4 with metabolic pathways and its significant expression differences in liver cancer, LIHC was selected for further investigation." (PMID 40004479, 2025). "In our in vitro studies, we observed that RBP4 regulates liver cancer cell migration and proliferation." (PMID 40004479, 2025). "All in all, these results underscore how crucial RBP4 is in the development of liver cancer and point out its promise as a viable therapeutic target." (PMID 40004479, 2025). "To investigate whether RBP4 affects the migration ability of liver cancer cells in vitro, we used siRNA to knock down the RBP4 gene in Huh7 cells and conducted a scratch assay to evaluate changes in cell migration." (PMID 40004479, 2025). "Additionally, studies have shown that certain retinoid drugs can inhibit tumor cell proliferation, further suggesting that RBP4 may act as a modulator of both metastatic potential and cell proliferation, particularly in the context of liver cancer." (PMID 40004479, 2025).
liver cirrhosis (4 papers, 2010 to 2024). "Patients with liver cirrhosis as the primary underlying diagnosis for ICU admission had significantly lower RBP4 levels as compared with other ICU patients." (PMID 20932285, 2010). "Consequently, patients with chronic liver diseases and liver cirrhosis have significantly decreased RBP4 serum concentrations, and serum RBP4 is directly linked to liver function in these patients." (PMID 20932285, 2010). "Interestingly, ICU patients with liver cirrhosis displayed the lowest RBP4 serum levels among all subgroups." (PMID 20932285, 2010).
lung carcinoma (4 papers, 2016 to 2024). "This study found limited evidence supporting a causal relationship between adiponectin, leptin, sOB-R, resistin, RBP4, or PAI-1 and sarcoidosis, asthma, COPD, lung cancer, tuberculosis, pneumonia, or sleep apnea syndrome." (PMID 38263093, 2024). "No significant causal relationships were found between leptin, sOB-R, resistin, RBP4, or PAI-1 and sarcoidosis, asthma, COPD, lung cancer, tuberculosis, pneumonia, and sleep apnea syndrome." (PMID 38263093, 2024).
microphthalmia (4 papers, 2017 to 2022). Congenital or developmental anomaly in which the eyeballs are abnormally small. "Finally, a heterozygous missense mutation in RBP4 was found to be responsible in an isolated case of bilateral complex microphthalmia." (PMID 29178648, 2017).
periodontitis (4 papers, 2020 to 2023). An acute or chronic inflammatory process that affects the tissues that surround and support the teeth. "In summary, our systematic review and meta-analysis presented more convincing details and comprehensive analysis about the association between RBP4/visfatin biofluid level and patients with periodontitis who are obese." (PMID 38132460, 2023). "RBP4 is also greatly associated with inflammation and oxidative stress, and the circulating levels of RBP4 were highest in obese rats with periodontitis in our study." (PMID 38069063, 2023). "Previous studies investigating the relationship between the local and systematic expression of RBP4, asprosin and periodontitis, especially associated with the obese status, was rather equivocal, and this became the problem we focused on addressing." (PMID 38069063, 2023). "In summary, it is meaningful and worthwhile to expect a deeper and therapeutic investigation of RBP4/visfatin in obese patients with periodontitis." (PMID 38132460, 2023). "The strong positive associations between the periodontal or circulating levels of RBP4 (or asprosin) and the degree of alveolar resorption in experimental periodontitis and obese rats were revealed." (PMID 38069063, 2023). "Further research should focus on revealing the role and mechanism of RBP4/visfatin in regulating bone defects in obese periodontitis subjects in vivo." (PMID 38132460, 2023). "Previous studies have shown either decreased or increased circulating levels of RBP4 in obese patients with periodontitis compared to those with normal weight." (PMID 38132460, 2023). "Furthermore, assessing the feasibility of treating alveolar bone resorption in obese patients with periodontitis using RBP4/visfatin monoclonal antibodies or blockers lays the groundwork for long-term clinical transformation and precise treatment." (PMID 38132460, 2023). "However, increased periodontal mRNA and protein expression levels of RBP4 in rats with periodontitis and the higher increased level in obese rats with periodontitis were found." (PMID 38069063, 2023). "The present study revealed a divergent adipokine expression profile, and notably a strong relationship between the expression of RBP4 and asprosin and the increased periodontal and circulating levels of RBP4 and asprosin in experimental periodontitis and diet-induced obese rats." (PMID 38069063, 2023). "Therefore, our study aimed to investigate the expression profile and possible role of RBP4, asprosin and other adipokines in experimental periodontitis and diet-induced obese rats." (PMID 38069063, 2023). "Also, a positive correlation between the gingival mRNA expression of RBP4/asprosin and CEJ-ABC was observed, which indicates that higher gingiva RBP4/asprosin expression levels might point to an increased probability of periodontitis in both lean and obese populations." (PMID 38069063, 2023).